KLK13 (kallikrein related peptidase 13)
Synonyms: KLK-L4; KLKL4
Tractability: Antibody: UniProt places it where antibodies can reach, with high confidence; its Gene Ontology location is reachable by antibodies, with high confidence; UniProt predicts a signal peptide or a membrane-spanning region. PROTAC: a small molecule that binds it is known.
Target class: Serine protease; Enzyme; Serine protease PA clan; Serine protease S1A subfamily; Protease
Gene: Protein-coding gene on chromosome 19 (51,055,626 to 51,065,114, reverse strand). Ensembl gene ENSG00000167759.
Subcellular location: Secreted
Pathways (Reactome):
Developmental Biology: Formation of the cornified envelope
Metabolism of proteins: Regulation of Insulin-like Growth Factor (IGF) transport and uptake by Insulin-like Growth Factor Binding Proteins (IGFBPs)
Gene Ontology:
Molecular function: hydrolase activity; protein binding; serine-type endopeptidase activity; endopeptidase activity
Biological process: protein maturation; proteolysis
Cellular component: cytoplasm; extracellular region; secretory granule
Genetic constraint (gnomAD): Loss-of-function variants: 20 observed, 23.46 expected, observed/expected ratio (o/e) 0.85, 90% interval 0.6 to 1.24. The upper end of that interval is the gene's LOEUF score, 1.24, which puts it in group 5 of 6, group 1 being the genes least tolerant of losing a copy. Missense variants: 309 observed, 352.28 expected, observed/expected ratio (o/e) 0.88, 90% interval 0.8 to 0.96. Synonymous variants: 156 observed, 143.88 expected, observed/expected ratio (o/e) 1.08, 90% interval 0.95 to 1.24.
Homologues: Orthologues: chimpanzee KLK13 (99% identical), macaque KLK13 (98% identical), dog KLK13 (82% identical), guinea pig KLK13 (79% identical), rat Klk13 (79% identical), mouse Klk13 (78% identical). Paralogues in human: KLK6 (45% identical), GZMB (35% identical), CMA1 (33% identical), CTSG (33% identical), GZMH (31% identical), AZU1 (26% identical).
Diseases named in the same sentence as KLK13 in open-access papers:
KLK13 is named in the same sentence as 40 diseases in open-access papers, as found by Europe PMC text mining. Sharing a sentence is not in itself a finding about the gene and the disease. The quoted sentences say what the papers report.
breast carcinoma (9 papers, 2002 to 2025). "Taken together, these data suggest that higher KLK13 expression in these subgroups of breast cancer patients is associated with an approximately 55 to 80% reduction in the risk of relapse or death." (PMID 11986781, 2002). "Further experiments using different patient groups should be conducted to determine if KLK13 expression is associated with the response to endocrine therapy in breast cancer and to elucidate the possible clinical utility in KLK13 expression." (PMID 11986781, 2002). "KLK13 is reported as an independent and favorable prognostic marker in breast cancer and ovarian cancer." (PMID 40156045, 2025). "Among the KLK11-14, KLK13 expression was reported as a favorable prognostic marker in breast cancers and ovarian cancers which is consistent with our present results." (PMID 37176127, 2023). "KLK13 gene was found to be regulated by steroid hormones in a human breast cancer cell line so that its expression is an independent favorable prognostic marker for breast carcinoma." (PMID 24288670, 2013). "Kallikrein-related peptidase 13 (KLK13) was first identified as downregulated in breast cancer tissues and cell lines." (PMID 19707197, 2009). "A low number of KLK1 and KLK13 mRNA messages were detectable in the MCF7 breast cancer cell line 3 h after oestradiol stimulation (16 tpm for each gene), but not in unstimulated cells (data not shown)." (PMID 14710225, 2004). "We conclude that KLK13 expression, as assessed by quantitative reverse transcriptase–polymerase chain reaction, is an independent favourable prognostic marker for breast carcinoma." (PMID 11986781, 2002). "Future studies should examine such a possible role of KLK13 in the management of patients with breast cancer." (PMID 11986781, 2002). "In this study, we demonstrate that KLK13 expression has an independent, favourable prognostic value in breast cancer." (PMID 11986781, 2002). "This study is the first to describe KLK13 as an independent favourable prognostic marker in breast cancer." (PMID 11986781, 2002). "We hypothesised KLK13 may be differentially expressed in breast cancer tissues and may have prognostic/predictive value." (PMID 11986781, 2002). "KLK13 could mediate its role either by generating or activating breast cancer inhibitory factor(s) or by terminating the action of unfavourable factor(s)." (PMID 11986781, 2002). "However, the mechanism to explain the role of KLK13 in breast cancer aggressiveness is still unknown." (PMID 11986781, 2002). "KLK12, KLK13, and KLK14 genes were downregulated in breast cancer, while KLK15 was overexpressed in more aggressive forms of prostate cancer." (PMID 33150763, 2020). "Other kallikrein genes, for example, KLK13 and KLK14, were also previously reported to be downregulated in breast cancer." (PMID 14710225, 2004). "The objective of this study was to further investigate the relationship between KLK13 expression and other clinicopathological variables and DFS and OS using, univariate and multivariate analysis for a group of 173 breast cancer patients." (PMID 11986781, 2002). "With respect to breast cancer in particular, several kallikrein family members, namely KLK3, KLK5, KLK6, KLK10, KLK12, KLK13, and KLK14 were shown to be differentially expressed at the mRNA or protein levels within the cancerous tissues or serum of such patients." (PMID 16434994, 2006).
ovarian carcinoma (6 papers, 2009 to 2025). A malignant neoplasm originating from the surface ovarian epithelium. "This study was aimed at examining the expression of KLK6 and KLK13 in ovarian cancer to determine their diagnostic or prognostic value." (PMID 19707197, 2009). "The expression of KLK13 mRNA in normal OSE was extremely low, whereas 55% ovarian cancers examined had high KLK13 expression." (PMID 19707197, 2009). "Similar to KLK6, KLK13 can degrade major components of the ECM and when treated with an anti-KLK13 antibody, an ovarian cancer cell line showed decreased migratory capacity." (PMID 19707197, 2009). "Our study is the first to report KLK13 mRNA expression in normal ovary and ovarian cancer patients." (PMID 19707197, 2009). "The aim of this study was to determine the prognostic significance of kallikrein-related peptidase 6 (KLK6) and kallikrein-related peptidase 13 (KLK13) in epithelial ovarian cancer by quantifying gene expression levels with tumour pathology and patient survival data." (PMID 19707197, 2009). "In all, this study shows KLK6 and KLK13 as potential biomarkers and may be therapeutic targets for treatment of ovarian cancer." (PMID 19707197, 2009). "High protein levels of KLK4–7 and KLK10 have been found in ovarian cancer tissues, while KLK5–8, KLK10, KLK11, KLK13 and KLK14 were found in ascites fluid from ovarian cancer patients as reviewed." (PMID 24043563, 2014). "The hierarchical clustering revealed a group of proteins that have previously been reported to be expressed at elevated levels in ovarian cancer serum samples, including: CA125 (MUC16), HE4, MSLN, MK, KLK8, KLK11, NECT4, FOLR1, as well as KLK13, KLK14, and IL6." (PMID 35804849, 2022).
breast tumors (2 papers, 2002 to 2019). "Kallikrein 13 (KLK13) was first identified as an enzyme that is downregulated in a subset of breast tumors." (PMID 30925705, 2019). "KLK13 was found to be down-regulated (at the mRNA level) in a preliminary set of 19 breast tumours." (PMID 11986781, 2002). "Previously, KLK13 was found to be down-regulated in a subset of 19 breast tumours." (PMID 11986781, 2002).
esophageal squamous cell carcinoma (2 papers, 2020 to 2025). Esophageal squamous cell carcinoma (ESCC) is a type of esophageal carcinoma (EC) that can affect any part of the esophagus, but is usually located in the upper or middle third. "Different expression levels of KLK13 have been shown to be associated with patient prognosis in esophageal squamous cell carcinoma and bladder cancer." (PMID 32858528, 2020). "Lastly, the CpG site cg26524263 also influences the methylation of the KLK13 gene, with decreased KLK13 expression correlating with poor survival in esophageal squamous cell carcinoma." (PMID 40177272, 2025).
melanoma (2 papers, 2011 to 2016). A malignant, usually aggressive tumor composed of atypical, neoplastic melanocytes. "The present study confirms these associations at the transcriptional level and shows that not only KLK6 and KLK7 but other hKLKs such as KLK8 and KLK13 are probably coordinately involved in melanoma progression." (PMID 22032772, 2011). "This study was the first to report a coordinated decrease in mRNA expression levels of hKLKs (KLK6, KLK7, KLK8 and KLK13) as melanoma cells emerges from primary to metastatic phenotype, suggesting a role of these proteases in the epithelial-mesenchymal transition of primary melanoma cells." (PMID 22032772, 2011). "For melanoma progression category (T3, T4 and MM), only genes ontologically-related to hKLKs (EVPL, KLK6, KLK7, KLK8, KLK13 and SERPINB13) showed a positive and high correlation coefficient (mean of 0.971) in T4 thick melanomas (depth > 4.0 mm), but not in metastatic tumors (MM)." (PMID 22032772, 2011).
atopic dermatitis (1 paper, 2019). "In homeostasis, human kallikrein 13 (KLK13) is primarily expressed in the testis, prostate, breast, salivary glands, esophagus and the cervix and is associated with certain skin pathologies, including psoriasis vulgaris and atopic dermatitis." (PMID 30925705, 2019).
breast invasive carcinoma (1 paper, 2018). "Five KLKs were commonly downregulated in head-neck squamous cell carcinoma and breast invasive carcinoma: KLK3 (3-fold and 4-fold), KLK6 (2-fold and 6-fold), KLK7 (2-fold and 10-fold), KLK11 (5-fold and 6-fold) and KLK13 (8-fold and 3-fold)." (PMID 29707153, 2018).
colon cancer (1 paper, 2009). "Nine KLKs (KLK5-8, KLK10, KLK11, KLK13-15) were measured using ELISA assays in cytosolic extracts of 122 colon cancer tissues and their nearby normal mucosa, obtained during surgery." (PMID 19367279, 2009).
COVID-19 (1 paper, 2025). A disease caused by infection with severe acute respiratory syndrome coronavirus 2. "We confirmed that KLK13 was secreted in the nasal mucus of both healthy individuals and COVID-19 patients." (PMID 41114586, 2025). "KLK13 was detected in the nasal mucus of both healthy and COVID-19 volunteers, in line with the previous nasal mucus proteomics studies (39, –, 41)." (PMID 41114586, 2025). "Currently, we have no epidemiological evidence indicating that the KLK13 H109Y mutation is associated with the disease severity of COVID-19 patients." (PMID 41114586, 2025).
endometrioid ovarian cancers (1 paper, 2009). "Interestingly, all endometrioid ovarian cancers had high KLK13 expression relative to normal ovaries, but the small sample size was unable to provide sufficient power for a conclusive association." (PMID 19707197, 2009).
endometriosis (1 paper, 2017). The growth of functional endometrial tissue in anatomic sites outside the uterine body. "We may speculate that the absence KLK13 in endometriosis could have a role in infertility." (PMID 28174513, 2017).
hepatocellular carcinoma (1 paper, 2018). A malignant tumor that arises from hepatocytes. "In hepatocellular carcinoma, increased expression of KLK13 was significantly associated with increase in mortality (HR = 1.75)." (PMID 29707153, 2018).
hypospadias (1 paper, 2020). Hypospadias is the displacement of the urethral meatus on the ventrum of the penis. "This region on chromosome 19 is characterized by clusters of sialic acid-binding Ig-like lectin (SIGLEC) and kallikrein (KLK) genes, among which we identified likely causal relationships with hypospadias (CD33/SIGLEC3, SIGLEC5, SIGLEC7, KLK5, KLK7, KLK10, KLK13, and KLK14)." (PMID 32728162, 2020).
lung carcinoma (1 paper, 2021). "KLK13 enhances the invasiveness and motility of lung cancer via increasing laminin degradation and N-cadherin expression." (PMID 34395235, 2021).
mucinous adenocarcinoma (1 paper, 2009). An invasive adenocarcinoma composed of malignant glandular cells which contain intracytoplasmic mucin. "Shown here is strong staining for both KLKs in serous adenocarcinoma, with KLK6 shown expressed in a mucinous adenocarcinoma and KLK13 expression in a clear cell tumour." (PMID 19707197, 2009).
Netherton syndrome (1 paper, 2022). Netherton syndrome (NS) is a skin disorder characterized by congenital ichthyosiform erythroderma (CIE), a distinctive hair shaft defect (trichorrhexis invaginata; TI) and atopic manifestations. "LEKTI can diminish the activities of epidermal serine proteases such as KLK5, KLK6, KLK7, KLK13, and KLK14 in skin, and a mutation in the SPINK5 gene is characteristic of Netherton syndrome, which presents with serious dehydration, itching, and chronic skin inflammation." (PMID 35955819, 2022).
oral cancer (1 paper, 2015). "Finally, down-regulation of KLK13 was reported in oral SCC cell lines and low KLK13 expression in primary oral cancer significantly correlated with regional lymph node metastasis." (PMID 25990935, 2015).
ovarian adenocarcinoma (1 paper, 2009). An adenocarcinoma that arises from the ovary. "Both KLK6 and KLK13 showed staining in all types of ovarian adenocarcinoma." (PMID 19707197, 2009).
ovarian tumours (1 paper, 2009). "High KLK6 or KLK13 expression in primary ovarian tumours can significantly predict prognosis in terms of recurrence-free survival and overall survival." (PMID 19707197, 2009).
skin cancer (1 paper, 2020). "In addition, KLK13 has been considered an independent favorable prognosis biomarker for several cancers, including skin cancer." (PMID 32413042, 2020).
virus infection (1 paper, 2025). "To further investigate the role of KLK13 in viral infection in vitro, we overexpressed KLK13 in A549-hACE2-TMPRSS2 cells." (PMID 41114586, 2025). "However, the presence of KLK13 in the nasal mucus likely contributes to reducing disease severity via restricting virus infection." (PMID 41114586, 2025). "Moreover, we checked the cleavage activity of KLK13 in the context of virus infection." (PMID 41114586, 2025). "To understand whether KLK13 is an interferon-stimulated gene (ISG), we stimulated both A549 and HeLa cells with poly(I:C), an analog of dsRNA that mimics the molecular pattern associated with viral infection." (PMID 41114586, 2025).
tumor (10 papers, 2002 to 2021). "The strength of association between KLK13 high expressing tumours and survival outcome is presented in a Cox regression model." (PMID 19707197, 2009). "KLK13 overexpression is reported to result in an increased tumor malignant potential, knockdown of its internal gene expression, and decreased cell migration and invasive characteristics." (PMID 33150763, 2020). "Cox multivariate analysis indicated that KLK13 was an independent prognostic variable in the subgroups of patients with Grade I–II tumours and in patients who were oestrogen receptor and progesterone receptor positive, and node positive." (PMID 11986781, 2002). "Furthermore, the prognostic impact of established clinical factors and the analyzed KLK5–7 and KLK13 concentrations in tumor tissue was also analyzed in this independent collective." (PMID 25436002, 2015). "Positive KLK13 expression is associated with a significantly larger increase in DFS and OS in both univariate and multivariate analyses and patients who are ER positive, node positive or have low grade tumours." (PMID 11986781, 2002).
cancer (8 papers, 2009 to 2020). A tumor composed of atypical neoplastic, often pleomorphic cells that invade other tissues. "Cytoband location 19q13.3–q13.4 was common for differentially expressed KLK gene family (KLK12, KLK11, KLK10, and KLK13), the serine proteases encoded from this Kallikrein gene family have been implicated in various cancers." (PMID 25505737, 2014). "Studies on KLK13 have predominantly focused on its applicability as a cancer biomarker, leaving the physiological role of this protein not well understood." (PMID 30647911, 2018). "Although its function is still unclear, KLK13 is used as a new cancer biomarker in various cancers, including prostate, breast, ovarian, salivary gland, testicular, and non-small cell lung cancers." (PMID 25056661, 2014). "Expression levels of both KLK6 and KLK13 mRNA were significantly increased in invasive cancers relative to normal ovaries (P=0.002 and 0.039 respectively)." (PMID 19707197, 2009). "Disruption of this interaction can allow KLK13 to react with other proteins, which may lead to cleavage in the major components of the extracellular matrix and help in the promotion of cancer cell growth, metastasis and invasion." (PMID 25056661, 2014). "The score, encompassing the clinical factors of ascitic fluid volume and nuclear grading, plus the cancer biomarkers KLK6 and KLK13, is designed to predict the efficiency of the intra-abdominal debulking procedure." (PMID 25436002, 2015). "In a previous study, we established the OVSCORE, an algorithm to predict surgical outcome, based on the clinical factors of nuclear grading and ascitic fluid volume, plus the cancer biomarkers, kallikrein-related peptidases (KLKs), KLK6 and KLK13." (PMID 25436002, 2015). "This score encompasses the clinically relevant factors of ascitic fluid volume and nuclear grading, plus two novel cancer biomarkers, the serine proteases KLK6 and KLK13." (PMID 25436002, 2015).
infection (1 paper, 2020). The state of being infected such as from the introduction of a foreign agent such as serum, vaccine, antigenic substance or organism. "In particular, HCoV-HKU1 infection was dependent on KLK13 activity, and HCoV-HKU1 did not replicate in HAE cells deficient in KLK13." (PMID 32405877, 2020).
KLK13 also shares sentences with these, for which no sentence is quoted: thyroid carcinoma (2 papers); bladder cancer (1); chromophobe renal cell carcinoma (1); clear cell renal cell carcinoma (1); colon adenocarcinoma (1); head-neck squamous cell carcinoma (1); Infertility (1); metastatic tumors (1); mucoepidermoid carcinoma (1); papillary renal cell carcinoma (1); prostate carcinoma (1); psoriasis (1); psoriasis vulgaris (1); serous adenocarcinoma (1); Sjögren’s syndrome (1); urothelial bladder carcinoma (1).